AR (androgen receptor)
Diseases named in the same sentence as AR in open-access papers (continued):
Sharing a sentence is not in itself a finding about the gene and the disease.
breast carcinoma (continued). "Moreover, in breast cancer, AR expression is inversely correlated with immune cell infiltration and cytotoxic immune activity, suggesting an immunosuppressive effect of AR signals." (PMID 36721218, 2023). "Growing evidence supports the existence of a potent interplay between SDCs and various types of nuclear receptors, specifically ER, PR, and AR, that contribute to breast cancer progression or regression, and that crosstalk will be discussed in the next section." (PMID 36980680, 2023). "The role of AR signaling in breast cancer has received much attention." (PMID 37099044, 2023). "AR expression in breast cancer is a disease prognostic marker." (PMID 36497214, 2022). "After knocking down AR in tamoxifen resistant breast cancer cells, tamoxifen sensitivity was restored, which might be the result of upregulation of the estrogen related classical signaling pathway." (PMID 36556209, 2022). "Regarding non-targeted therapy, AR expression has also been found to be positively associated with and predictive of response to neoadjuvant chemotherapy in breast cancer." (PMID 35203574, 2022). "Because malignant breast tumors often express AR, some literature evidence showed that combination of tamoxifen and anti-AR therapies could be a potential therapeutic strategy for patients with breast cancer and SARS-CoV-2 infection." (PMID 35399920, 2022). "However, AR-mediated androgenic stimulation has diverse effects in growth of breast cancer cells and the role of AR in breast cancer progression is unclear." (PMID 36178912, 2022). "AR is reported as being positive in 60–90% of primary breast cancers." (PMID 36527133, 2022). "Similarly, in HER2-positive breast cancer cases, AR status is inversely correlated with CD3-positive and CD8-positive T cell infiltration." (PMID 37435447, 2022). "Radiation therapy (RT) and hormone receptor (HR) inhibition are used for the treatment of HR-positive breast cancers; however, little is known about the interaction of the androgen receptor (AR) and estrogen receptor (ER) in response to RT in AR-positive, ER-positive (AR+/ER+) breast cancers." (PMID 35618789, 2022). "Moreover, the correlation between ZMIZ2 and AR in different subtypes of breast cancers was calculated." (PMID 35101047, 2022). "Furthermore, in breast cancer, AR was shown to play an important role in promoting the growth of HER2-positive disease by a functionally significant cross-talk with the HER2 signaling." (PMID 36733354, 2022). "It has been shown that high level of AR expression are found in 70–90% breast cancer." (PMID 35595729, 2022). "Therefore, the AR expression is routinely monitored to establish a preliminary diagnosis and drug target for therapeutic clinical management of prostate and breast cancers." (PMID 36045397, 2022). "For ERα+ve breast cancer, activation of the AR had been demonstrated to suppress the disease." (PMID 36499670, 2022). "There are 70–90% of breast cancer patients who express the AR, with several studies indicating that AR might be a predictive or prognostic factor and a drug target in breast cancer." (PMID 35054486, 2022). "Androgen receptor is known to be expressed in up to 90% of breast cancers and around 30% of TNBCs." (PMID 35444182, 2022). "Given the crucial role of AR in breast cancer progression and the fact that AR is a substrate of Src, to which Kindlin-2 binds, we decided to focus on the role and mechanism of Kindlin-2-mediated regulation of AR tyrosine phosphorylation, signaling and breast cancer progression in the current study." (PMID 35595729, 2022). "Clinical trials using AR antagonists in breast cancer are active." (PMID 35053220, 2022). "A study suggested that 5’ untranslated region mutation (T105A) of AR promotor was identified from AR-negative breast cancer patients, and could affect AR expression." (PMID 35053220, 2022).
breast carcinoma (continued). "According to a study by Gucalp, male breast cancer is almost exclusively hormone receptor positive (+), including androgen receptor (AR), and is associated with a higher prevalence of BRCA2 germline mutations, particularly in men at an increased risk for developing high-risk breast cancer." (PMID 35885460, 2022). "In future, the inclusion of the AR status in the breast cancer report at the time of diagnosis might help improve disease classification and treatment decision, thereby providing additional treatment strategies for breast cancer." (PMID 36499670, 2022). "Top 10 contributing authors in the field of androgen receptor and breast cancer." (PMID 35800434, 2022). "Whether AR’s expression level and activity in breast cancer are also related to epigenetic modification is poorly understood." (PMID 35053220, 2022). "Furthermore, AR expression is maintained in recurrent breast cancer tissues after AI treatment, while ERα and PR expression levels are significantly downregulated." (PMID 37435447, 2022). "In this sub-type of breast cancer, AR acts as a good prognostic factor." (PMID 35053220, 2022). "We next asked whether FOXA1 binds directly to AR gene sequences, promoting AR expression in breast cancer cells." (PMID 36171192, 2022). "However, the clinical significance of AR expression is still controversial and the biological function of androgens in breast cancers is unclear." (PMID 37435447, 2022). "Furthermore, relatively higher expression of AR compared to ERα (AR:ERα ratio ≥ 2) correlates with shorter disease-free and disease-specific survival in ERα-positive breast cancers." (PMID 37435447, 2022). "However, AR stimulates tumor cell progression in ER-negative (ER−) breast cancers and is becoming an emerging molecular target in TNBC." (PMID 35768871, 2022). "The expression of AR is often detected in about 60% to 90% of ER + ve breast cancer cases." (PMID 35053220, 2022). "AR stimulates tumor development and progression in ER− breast cancers." (PMID 35768871, 2022). "Additionally, both hormones decreased the expression of AR in a variety of tissues, including breast cancer and endometrium." (PMID 36263327, 2022). "Interestingly, resembling AR + ve/ER + ve breast cancers, studies have emphasized that patients with LAR type cancers had a favorable prognostic outcome with lower KI-67 levels, lower tumor grade, and higher OS." (PMID 35053220, 2022). "The roles of the AR should be clarified in different subtypes of breast cancer." (PMID 36499670, 2022). "Despite initial studies that suggested a potential negative prognostic role of AR, recently, much evidence indicated that AR expression associated with a favorable prognosis in this type of breast cancer." (PMID 35761157, 2022). "AR positivity was also associated with significantly better OS in AR+ non-luminal HER2 positive breast cancer treated with neoadjuvant chemotherapy." (PMID 35207749, 2022). "Although AR antagonists are normally used as a standard of care for prostate cancer, androgen deprivation agents have additionally shown anti-tumor efficacy against breast cancer in preclinical studies as well." (PMID 36497086, 2022). "Approximately, 70–95% of ER+/HER2− breast cancers do also express the androgen receptor (AR)." (PMID 37435469, 2022). "Moreover, in ER-positive and ER-negative cancer, the expression of AR was reported to have opposite prognostic values as AR expression was correlated with increased DFS in luminal breast cancer and decreased DFS in triple-negative breast cancer (TNBC)." (PMID 36232774, 2022). "In a nutshell, our findings suggest that AR may play role in genetic ancestry and could play a role in the regulation of gene expression in aggressive type breast cancer." (PMID 36550153, 2022).
breast carcinoma (continued). "Since little is known regarding QNBC-specific miRNA regulatory networks, much of the data driving hypotheses for miRNA regulation affecting QNBC pathobiology are extrapolated from the study of TNBC, AR function in breast cancer, and from other cancers." (PMID 35203574, 2022). "Furthermore, we provide evidence showing that Kindlin-2 forms a supramolecular complex with both AR and Src and thereby promotes Src-mediated Tyr-534 phosphorylation of AR, breast cancer cell migration and proliferation." (PMID 35595729, 2022). "The androgen receptor (AR) is also expressed in >70% of breast carcinoma tissues." (PMID 37435447, 2022). "Remarkably, it has been reported that around 70–90% of breast cancers are detected as AR+ve cases, implicating that the AR may play some roles in disease development and progression." (PMID 36499670, 2022). "Additionally, the Nurses Health Study revealed that 77% of invasive female breast cancers were androgen-receptor (AR)-positive." (PMID 36497561, 2022). "Previous studies have shown that DHT-activated AR interacts with demethylase LSD1 to repress E-cadherin transcription and upregulate vimentin transcription in the ER and AR positive MCF7 breast cancer cells, leading to EMT that increases cell migration and invasion." (PMID 35960413, 2022). "There may be some heterogeneity in endocrine–resistant breast cancers, and the role of AR remains to be elucidated through in–depth studies." (PMID 36556209, 2022). "There should be a similar regulatory mechanism of AR expression in breast cancer." (PMID 35053220, 2022). "SETDB1 was reported to suppress androgen receptor and PR expression in T47D breast cancer cells." (PMID 36230806, 2022). "USP14 plays an anti-apoptotic role in breast cancer via AR deubiquitination." (PMID 35884607, 2022). "One of the potential factors is that AR may have different biological functions and signal pathways in breast cancer." (PMID 36556209, 2022). "Modulating the activity of the AR will be a promising strategy for treating breast cancer." (PMID 36499670, 2022). "In HER2+ve breast cancer, it has been reported that an active AR could induce the expression of HER2, which subsequently activates the MAPK pathway." (PMID 36499670, 2022). "Androgen receptor (AR) signaling plays important roles in breast cancer progression." (PMID 35595729, 2022). "In hormone-dependent prostate and breast cancers, AR activation leads to tumor progression." (PMID 36291090, 2022). "Finally, although our current study focuses on breast cancer, abnormal AR signaling is known to be involved in malignancies in other organs (e.g., prostate) as well as several other pathological processes." (PMID 35595729, 2022). "These clinical studies supported that AR expression could be a useful prognostic factor in breast cancers." (PMID 35053220, 2022). "Finally, using a genetic knockout strategy, we show that Kindlin-2 is crucial for AR signaling and breast cancer progression in vivo." (PMID 35595729, 2022). "However, other types of breast cancer, including luminal androgen receptor–positive TNBC, expressed lower levels of TM4SF." (PMID 35153775, 2022). "The AR signaling pathway differs according to molecular breast cancer subtypes." (PMID 35052843, 2022). "AR is emerging as a promising prognostic biomarker and it may serve as a potential therapeutic target for treatment of breast cancer." (PMID 35595729, 2022). "Taken together, these data support our hypothesis that the effects of Kindlin-2 on AR signaling and breast cancer cell behaviors are mediated, at least in part, by controlling AR Tyr-534 phosphorylation level." (PMID 35595729, 2022). "In the future, AR will be a feasible biomarker for breast cancer." (PMID 35053220, 2022). "Additionally, AR can be a target of specific treatment and there are several ongoing clinical trials of anti-androgenic agents for breast cancers expressing." (PMID 36178912, 2022).
breast carcinoma (continued). "The androgen receptor (AR) is a steroid hormone receptor widely detected in breast cancer." (PMID 36499670, 2022). "In this study, TNAC showed the same pattern as luminal breast cancer, which could be attributed to the expression of AR and other luminal genes in TNAC." (PMID 35329934, 2022). "The expression of AR is closely related to various subtypes of breast cancer." (PMID 35311116, 2022). "ERα and AR are co-expressed and directly interact with each other in breast cancer cells." (PMID 37435447, 2022). "Altogether these findings indicate a novel role for AR and ER signaling in AR+/ER+ breast cancer compared to the role of AR in TNBC or ER in AR-low/ER+ breast cancer models in response to radiation treatment with important clinical implications for this subset of patients." (PMID 35618789, 2022). "Finally, using a genetic knockout strategy, we show that ablation of Kindlin-2 from mammary tumors in mouse significantly reduced AR Tyr-534 phosphorylation, breast tumor progression and metastasis in vivo." (PMID 35595729, 2022). "We evaluated differential expression profiles of PR, AR, and MR genes between tumor samples from TCGA breast cancer patients and adjacent normal tissue and found that PR and AR were over-expressed while MR gene is under-expressed in breast cancer patients compared to normal tissue." (PMID 34421361, 2021). "Furthermore, we discuss the potential crosstalk between the two most abundant adipokines produced by the adipose tissue (adiponectin and leptin) and the androgen receptor, an emerging marker in breast cancer." (PMID 34066328, 2021). "Here, we disclosed GT0918, a 2nd-generation AR antagonist, for breast cancer treatment." (PMID 34392453, 2021). "For instance, AR could reduce the expression of miR-21 in breast cancer, while inducing its expression in hepatocellular carcinoma." (PMID 34831421, 2021). "The results of our study indicated that our radiomics model might predict molecular subtype and AR expression non-invasively and significantly avoid unnecessary biopsy for breast cancer patients." (PMID 34490107, 2021). "Both PDGFR-β and AR are very important prognostic markers for breast cancer patients." (PMID 34659545, 2021). "Our study showed that some specific radiomics features extracted from multi-parametric MRI could predict molecular subtype and AR status in breast cancer." (PMID 34490107, 2021). "In addition, p68 cooperates with PDGFR-β to co-regulate AR expression, therefore facilitates androgen dependent proliferation in breast cancer cells." (PMID 34659545, 2021). "The AR and ER promote tumor growth in hormone-dependent prostate and breast cancer, respectively." (PMID 34201346, 2021). "We similarly noted that basal-like breast cancer patient tumors had the lowest AR expression." (PMID 34072264, 2021). "Comparative RNA expression analysis of genes associated with receptor status in Study biopsy #2: ESR1 (ER), PGR (PR), ERBB2 (HER2) and AR, showed high RNA expression in relation to basal intrinsic subtypes from The Cancer Genome Atlas (TCGA) primary breast cancer cohort." (PMID 33772089, 2021). "Moreover, miR-9-5p can decrease the activity of AR-downstream signals, even in the conditions that breast cancer cells are induced by AR-agonists." (PMID 34831421, 2021). "This hypothesis can explain why patients with ER-positive and AR-positive breast cancer have better prognosis than patients with ER-negative and AR-positive breast cancer." (PMID 34392453, 2021). "This suggests that in the higher AR expressing ER+ breast cancer cell lines cultured in androgen-containing media, PART1 expression may be at least partially dependent on androgen signaling." (PMID 34072264, 2021). "As USP14 has been reported to be essential for breast cancer cell growth through the degradation of AR, it might be feasible to treat AR-positive breast cancer via the inhibition of USP14." (PMID 35069211, 2021).
breast carcinoma (continued). "This suggests that AR signaling may help induce new breast cancers, but “dedifferentiated” primitive cancers may downregulate AR expression because they are driven by hormone-independent mechanisms." (PMID 34768683, 2021). "Trastuzumab and lapatinib are anti HER-2 targeted therapies and may work for prevention of HER2+ breast carcinomas; bicalutamide and enzalutamide are AR antagonists that may impact the disease course of AR+ TNBCs." (PMID 34439109, 2021). "MDA-MB-453 cells overexpress androgen receptor and could also be characterised as an apocrine subtype breast cancer cell line, perhaps partly explaining the relative insensitivity of this cell line to HER2-targeted TKIs." (PMID 33473169, 2021). "A large number of studies used TNBC cell lines, each of which has a characteristic feature regarding the expression pattern of AR or ER-β, and examined the effect of suspected agonists or antagonists, including agents used in endocrine therapy for prostatic or breast cancer." (PMID 34070471, 2021). "Higher levels of AR expression are seen in breast cancers of older women." (PMID 34234742, 2021). "However, the bulk of positive evidence supports an anti-proliferative role of androgens in ER+ breast cancers, with androgenic signalling via AR generally antagonistic of oestrogen activity." (PMID 34638457, 2021). "AR may play different roles in breast cancer progression depending on the HR or HER2 amplification status." (PMID 34392453, 2021). "Moreover, USP14 expression has a positive correlation with AR expression according to the results from the TCGA database, and is remarkably high in all subtypes of breast cancer." (PMID 34575114, 2021). "Taken together, AR is expressed in many breast carcinomas, but cannot be used as an independent biomarker, whereas SOX10 could be." (PMID 33915941, 2021). "Thus, detecting molecular subtype and AR expression of breast cancer is important for treatment selection and predicting therapeutic response." (PMID 34490107, 2021). "However, male breast cancer, in contrast with the female CADs here studied, showed mainly X chromosome polysomy and related AR gene copy number gain." (PMID 33534004, 2021). "In order to investigate whether protein expression of the candidate genes was also AR regulated, nine AR expressing breast cancer cell lines were analyzed for PSA, ZAG and PIP protein in whole cell lysates and conditioned media." (PMID 34736512, 2021). "Nevertheless, the role of AR in breast cancer remains unclear and therefore it is cardinal that its function is thoroughly researched." (PMID 33915941, 2021). "AR expression in breast cancer has been shown to limit effects of PARPi in preclinical models and may explain the indifference of the tumor in case 1 to PARP inhibition." (PMID 34667258, 2021). "Historically, the study of NR function in breast cancer has largely focused on characterising and therapeutically targeting the oestrogen (ER) and, to a lesser extent, the progesterone (PR) and androgen receptors (AR)." (PMID 34638457, 2021). "Additionally, AR as a therapeutic target is under the clinical investigation for breast cancer, especially in the TNBCs or tumors resistant to first-line targeted therapy." (PMID 34490107, 2021). "in AR-positive breast cancer cells and its down-regulation may contribute at least in part to the anti-proliferative and anti-metastatic effects of androgen receptor inhibitors." (PMID 33915941, 2021). "Therefore, PART1 expression can be amplified by the presence of androgenic signaling molecules in AR expressing breast cancer cell lines (e.g., ER+ T47D cells)." (PMID 34072264, 2021). "Nevertheless, some triple-negative breast cancers express androgen receptor (AR), which could be used as a novel therapeutic target in such subgroup of breast cancers." (PMID 33915941, 2021). "However, we also validated this analysis using another androgen-responsive gene set derived from an AR-positive breast cancer cell line MDA-MB-453." (PMID 34736512, 2021).